UROS (uroporphyrinogen III synthase)
Description:
Catalyzes cyclization of the linear tetrapyrrole, hydroxymethylbilane, to the macrocyclic uroporphyrinogen III, the branch point for the various sub-pathways leading to the wide diversity of porphyrins. Porphyrins act as cofactors for a multitude of enzymes that perform a variety of processes within the cell such as methionine synthesis (vitamin B12) or oxygen transport (heme).
Synonyms: UROIIIS; Mgu
Tractability: PROTAC: ubiquitination databases record sites on it.
Target class: Enzyme; Lyase
Gene: Protein-coding gene on chromosome 10 (125,784,980 to 125,823,288, reverse strand). Ensembl gene ENSG00000188690.
Subcellular location: Cytoplasm, cytosol
Subcellular location (Human Protein Atlas): Nucleoplasm; Cytosol
Pathways (Reactome):
Metabolism: Heme biosynthesis
Gene Ontology:
Molecular function: uroporphyrinogen-III synthase activity; folic acid binding
Biological process: heme B biosynthetic process; heme biosynthetic process; uroporphyrinogen III biosynthetic process; cellular response to amine stimulus; cellular response to arsenic-containing substance; heme A biosynthetic process; response to platinum ion; tetrapyrrole biosynthetic process
Cellular component: cytosol; mitochondrion
Genetic constraint (gnomAD): Loss-of-function variants: 19 observed, 36.79 expected, observed/expected ratio (o/e) 0.52, 90% interval 0.36 to 0.76. The upper end of that interval is the gene's LOEUF score, 0.76, which puts it in group 3 of 6, group 1 being the genes least tolerant of losing a copy. Missense variants: 293 observed, 329.51 expected, observed/expected ratio (o/e) 0.89, 90% interval 0.81 to 0.98. Synonymous variants: 114 observed, 125.53 expected, observed/expected ratio (o/e) 0.91, 90% interval 0.78 to 1.06.
Gene-disease validity (ClinGen):
ClinGen rates the evidence that UROS causes each of these diseases.
cutaneous porphyria (autosomal recessive): Definitive. An erythropoietic porphyria (massive accumulation of photoreactive porphyrins in the bone marrow erythroid cells and circulating erythrocytes, resulting in cutaneous photosensitivity) caused by biallelic variants in UROS (in an autosomal recessive inheritance pattern).
Homologues: Orthologues: chimpanzee UROS (99% identical), pig UROS (89% identical), guinea pig UROS (86% identical), macaque UROS (85% identical), dog UROS (84% identical), mouse Uros (78% identical), rat Uros (78% identical), tropical clawed frog uros (56% identical), zebrafish uros (54% identical), Drosophila melanogaster Uros1 (34% identical), Drosophila melanogaster Uros2 (25% identical).
Diseases named in the same sentence as UROS in open-access papers:
UROS is named in the same sentence as 19 diseases in open-access papers, as found by Europe PMC text mining. Sharing a sentence is not in itself a finding about the gene and the disease. The quoted sentences say what the papers report.
Congenital erythropoietic porphyria (19 papers, 2007 to 2026). "Congenital erythropoietic porphyria (CEP), also known as Gunther's disease, is an uncommon autosomal recessive disorder caused by a mutation in the uroporphyrinogen III synthase gene." (PMID 38576642, 2024). "Firstly, congenital erythropoietic porphyria (CEP) is most often caused by a deficiency in uroporphyrinogen III synthase (UROS), the fourth enzyme of the heme biosynthesis pathway." (PMID 34940556, 2021). "Patients with this condition, also known as Gunther’s disease, have reduction-of-function mutations in uroporphyrinogen III synthase (UROS), the 4th enzyme in heme biosynthesis, and consequently produce high levels of porphyrins in their erythroid cells (Discussion)." (PMID 27240733, 2016). "Congenital erythropoietic porphyria (CEP), also known as Günther’s disease, results from a deficient activity in the fourth enzyme, uroporphyrinogen III synthase (UROIIIS), of the heme pathway." (PMID 34071291, 2021). "Background and Clinical Significance: Congenital erythropoietic porphyria (CEP), also known as Günther disease, is a rare autosomal recessive porphyria caused by a deficiency of uroporphyrinogen III synthase, leading to the accumulation of phototoxic type I porphyrins." (PMID 41718315, 2026). "Congenital erythropoietic porphyria (CEP) is a rare inherited metabolic disorder caused by mutations in the UROS gene, in which lead to deficient activity of the enzyme uroporphyrinogen III synthase activity." (PMID 40230347, 2025). "One such example is congenital erythropoietic porphyria (CEP), most commonly caused by loss of function mutation in uroporphyrinogen III synthase (UROS), the enzyme that catalyzes the third step of the heme biosynthetic pathway." (PMID 33953217, 2021). "For example, congenital erythropoietic porphyria (CEP [MIM 263700]) is an autosomal recessive disorder characterized by a deficiency in the enzymatic activity of uroporphyrinogen III synthase (UROS; EC 4.2.1.75), the fourth enzyme of the heme biosynthetic pathway." (PMID 30850590, 2019). "Congenital erythropoietic porphyria (CEP), or Gunther disease, is a rare genetic disease responsible for severe dermatologic, hepatic and/or haematological damages related to the deficient activity of the uroporphyrinogen III synthase." (PMID 38577034, 2024). "Congenital erythropoietic porphyria (CEP; OMIM 263700), also named Günther’s disease, is a rare inborn error of heme biosynthesis, due to uroporphyrinogen III synthase (UROS; EC 4.2.1.75) deficiency." (PMID 38255745, 2024). "Congenital erythropoietic porphyria (CEP), a rare form of porphyria, is caused by a defect in the heme biosynthesis pathway of the enzyme uroporphyrinogen III synthase (UROS)." (PMID 36217751, 2023). "Congenital erythropoietic porphyria (CEP) is a rare genetic disorder leading to accumulation of uro/coproporphyrin-I in tissues due to inhibition of uroporphyrinogen-III synthase." (PMID 33953217, 2021). "Congenital erythropoietic porphyria (Günther disease) (CEP) is a rare autosomal recessive disorder that affects the enzyme uroporphyrinogen III synthase." (PMID 28899405, 2017). "Congenital erythropoietic porphyria (CEP, OMIM #263700), also known as Gunther’s disease, is a rare autosomal recessive disorder caused by mutations in the UROS gene, leading to reduced activity of uroporphyrinogen-III-synthase (UROS)." (PMID 40230347, 2025). "There are studies highlighting its ability to stabilize mutant enzymes like uroporphyrinogen III synthase (UROIIIS) in congenital erythropoietic porphyria, and combat multidrug-resistant Gram-negative bacteria." (PMID 40942125, 2025). "On the other hand, defects in FECH or UROS do not severely impair heme biosynthesis in the liver but instead result in the onset of erythropoietic protoporphyria (EPP) or congenital erythropoietic porphyria (CEP)." (PMID 26557657, 2015).
erythropoietic porphyria (13 papers, 2014 to 2025). "The first type is congenital erythropoietic porphyria (CEP) caused by uroporphyrinogen III synthase (UROS) deficiency, leading to accumulation of uroporphyrins and coproporphyrins." (PMID 39965404, 2025). "UROS, an enzyme associated with congenital erythropoietic porphyria, participates in the heme biosynthesis pathway." (PMID 34568059, 2021). "UPI is known to accumulate in the body in congenital erythropoietic porphyria due to enzyme defects in UROS." (PMID 34576284, 2021). "While coding mutations in UROS have been identified in over 50% of patients with congenital erythropoietic porphyria, rare mutations that disrupt a constrained GATA1 binding site in the first intron of UROS have been found in patients lacking a putative coding mutation." (PMID 25521328, 2014).
porphyria (8 papers, 2017 to 2024). Porphyria is a group of diseases in which substances called porphyrins build up, negatively affecting the skin or nervous system. "These SNPs are located in genes known to cause different kinds of porphyria, e.g. UROS and CPOX genes." (PMID 31824661, 2019). "This kind of porphyria is caused by deficient activity of uroporphyrinogen-III synthase (UROS), the fourth enzyme in the heme biochemical pathway." (PMID 29553924, 2018). "Uroporphyrins are produced in porphyrias with decreased activity of PBGD, UROS, and UROD." (PMID 29238562, 2017).
erythropoietic protoporphyria (3 papers, 2014 to 2026). A rare congenital metabolic disorder characterized by an inborn error of porphyrin-heme biosynthesis. "Genetic testing identified a low-penetrance intronic UROS variant typically associated with erythropoietic protoporphyria, underscoring diagnostic challenges and genotype-phenotype discordance." (PMID 41718315, 2026).
glioma (3 papers, 2016 to 2021). A benign or malignant brain and spinal cord tumor that arises from glial cells (astrocytes, oligodendrocytes, ependymal cells). "In this sense, we recently observed significant differences in the mRNA expression in 8 of 11 analyzed genes (HMBS, UROD, FECH, PPOX, SLC15A2, ALAD, UROS, and ABCB6) involved in the heme biosynthesis between WHO grade II and IV gliomas." (PMID 33562253, 2021). "Significant differences in mRNA expression included increases of HMBS, UROD, FECH and PPOX as well as decreases of SLC15A2, ALAD, UROS and ABCB6 in WHO IV gliomas." (PMID 32722247, 2020).
Splenomegaly (2 papers, 2011 to 2022). Abnormal increased size of the spleen. "CEP is a very rare genetic autosomal recessive disease, with mutation in the gene that codifies uroporphyrinogen-III synthase, leading to porphyrin accumulation in many tissues, with marked skin photosensitivity, hemolytic anemia with splenomegaly and a decreased life expectancy." (PMID 21731282, 2011).
leukemia (1 paper, 2022). A malignant (clonal) hematologic disorder, involving hematopoietic stem cells and characterized by the presence of primitive or atypical myeloid or lymphoid cells in the bone marrow and the blood. "We found a strong dependency for COX15, HMBS, and UROS in leukemia cells." (PMID 36450243, 2022). "To validate the function of SETD1A target genes (COX15, HMBS, UROS, RRNAD1, NUDT18, GSTZ1, HINT2, and COX18) in leukemia cells, we performed a CRISPR-based competitive cell proliferation assay in doxycycline-inducible Cas9-expressing MOLM-13 leukemia cells." (PMID 36450243, 2022).
nonimmune hydrops fetalis (1 paper, 2017). "CEP is an autosomal recessive disorder affecting the enzyme uroporphyrinogen III synthase, resulting in clinical manifestations ranging from nonimmune hydrops fetalis to a mild form of cutaneous photosensitivity lesions in adult life." (PMID 28899405, 2017).
ovarian carcinoma (1 paper, 2023). A malignant neoplasm originating from the surface ovarian epithelium. "The expression of ALAS2 and HMBS involved in iron utilization was associated with improved PFS in ovarian cancer, whereas expression of ABCB7, ALAD, FXN, UROS, ISCU, and CPOX in this process was associated with poor PFS in ovarian cancer." (PMID 38186569, 2023).
cancer (2 papers, 2019 to 2022). A tumor composed of atypical neoplastic, often pleomorphic cells that invade other tissues. "In living cancer cells, HMB is converted to uroporphyrinogen III (UPG III) by uroporphyrinogen III synthase (UROS)." (PMID 35742921, 2022).
tumor (2 papers, 2021 to 2022). "Greater UROS expression was noted in breast cancer and in tumor biopsies from head and neck cancer patients." (PMID 35055109, 2022).
UROS also shares sentences with these, for which no sentence is quoted: genetic disease (2 papers); autosomal recessive disease (1); Hodgkins lymphoma (1); metabolic disorder (1); non-Hodgkin lymphoma (1); rheumatoid arthritis (1); sarcoma (1); superficial epidermolytic ichthyosis (1).